TXNIP (thioredoxin interacting protein)
Diseases named in the same sentence as TXNIP in open-access papers (continued):
Sharing a sentence is not in itself a finding about the gene and the disease.
metabolic disorders (29 papers, 2013 to 2025). "A novel TXNIP loss-of-function variant, that impairs AA endocytosis, causes a rare metabolic disease." (PMID 41116060, 2025). "The characterization of a novel TXNIP loss-of-function variant in a patient with a severe metabolic disease further supports its role in nutrient homeostasis and human health." (PMID 41116060, 2025). "In particular, accumulated data provided strong evidence that TXNIP inhibition is a potential therapeutic approach for metabolic disorders and associated diseases." (PMID 33803178, 2021). "In conclusion, our results suggest that decreased TXNIP DNA methylation and increased gene expression are unlikely to represent major pathogenic mechanisms in fetal programming of metabolic disease caused by exposure to maternal diabetes." (PMID 29077742, 2017). "Modulating TXNIP expression or function may reduce the incidence of medial calcification in patients with cardiovascular diseases linked to metabolic disorders." (PMID 40610750, 2025). "In addition, we identified a novel biallelic loss-of-function TXNIP variant in a boy with a severe inborn metabolic disease." (PMID 41116060, 2025). "TXNIP can also affect tumorigenesis through its association with metabolic disorders." (PMID 37794178, 2023). "Consequently, dysregulation of this TXNIP-Trx axis is strongly associated with metabolic diseases." (PMID 37794178, 2023). "The in vivo effects were examined using a murine model of hindlimb ischemia to observe the physiological relevance of TXNIP modulation under metabolic disorders." (PMID 39075518, 2024). "Recent studies have shown that TXNIP is a critical signal that links inflammation and ER stress to cancers, cardiac diseases, and other metabolic diseases." (PMID 36830016, 2023). "Some researchers reported that silencing of TXNIP improved ischemia-induced revascularization in metabolic disorders." (PMID 35562171, 2022). "In contrast, a large amount of data strongly supports that TXNIP inhibition can be used to treat metabolic disorders and related diseases." (PMID 36059548, 2022). "Recent studies indicate an evolving role of TXNIP in the pathogenesis of complex diseases such as metabolic disorders, neurological disorders, and inflammatory illnesses." (PMID 33803178, 2021). "Peptides also contribute to inhibiting TXNIP and are useful for the prevention of several disorders (neurological and metabolic disorders)." (PMID 33803178, 2021). "More interestingly, reduced endothelial expression of TXNIP is associated with an increased TRX and decreased NADPH oxidase expression protecting the endothelium from dysfunction induced by metabolic disorders." (PMID 33567593, 2021). "Recent reports have shown TXNIP is a critical signal that links ER stress and inflammation to metabolic diseases like cancer, heart diseases, and other metabolic diseases." (PMID 31505737, 2019). "Correlations between TXNIP DNA methylation and gene expression and offspring markers of metabolic disease." (PMID 29077742, 2017). "Thus, TXNIP shuffles between TRX and GLUT to orchestrate the intracellular redox potential and glucose transport, suggesting that TXNIP is a promising therapeutic target for metabolic diseases." (PMID 38329960, 2024). "Moreover, targeting specifically endothelial TXNIP protects from metabolic-disorder-related impairment in post-ischemic revascularization and tissue recovery." (PMID 33567593, 2021). "Notably, these metabolic disorder phenotypes resemble the phenotypes which TXNIP-WKO exhibit under fasting conditions." (PMID 32824669, 2020). "Additionally, TXNIP inhibition is a potential target in the treatment of metabolic disorders, which might be interesting in light of epigenetic regulation of the TXNIP gene." (PMID 36791658, 2023). "TXNIP induces oxidative stress, inflammation, and pyroptosis through the activation of the NLRP3 inflammasome in metabolic disorders." (PMID 39629879, 2025).
metabolic disorders (continued). "Our work discovers a fundamental connection between ROS and glucose metabolism through TXNIP and provides a promising target for drug developments against GLUT-related metabolic diseases." (PMID 38329960, 2024). "Our findings establish a fundamental link between ROS and glucose metabolism through TXNIP and provide a promising target for the drug development against GLUT-related metabolic disorders." (PMID 38329960, 2024). "The ROS/TXNIP pathway is also involved in the pathogenesis of several metabolic diseases such as intervertebral disc degeneration and non-alcoholic fatty liver disease." (PMID 36059548, 2022).
neurodegenerative disease (25 papers, 2018 to 2025). A disorder of the central nervous system characterized by gradual and progressive loss of neural tissue and neurologic function. "It is interesting to note that other studies highlighted the role of TXNIP in other neurodegenerative diseases, such as AD, suggesting its causative role in the disease itself and a potential role as a therapeutic target." (PMID 40868900, 2025). "TXNIP has been implicated in neurodegenerative diseases, but there have only been a limited number of studies on this topic." (PMID 33302545, 2020). "Alterations in the expression of TXNIP have also been identified in blood cells from patients with multiple sclerosis (MS), a degenerative disease of white matter associated with autoimmune responses to myelin." (PMID 33302545, 2020). "TXNIP, thioredoxin interacting protein, is associated with neurodegenerative diseases." (PMID 36819777, 2023). "Overexpression of TXNIP can be caused by various signals, such as nutritional stimuli, glucose, amino acids, and insulin, suggesting the significance of TXNIP in the regulation of metabolic and neurodegenerative diseases." (PMID 33803178, 2021). "The exploration and development of inhibitors targeting TXNIP have marked significant advancements in the field of medical research, particularly in the context of chronic and degenerative diseases." (PMID 38790650, 2024). "Independent observations found increased levels of TXNIP in neurodegenerative disease and low levels of SELENOM." (PMID 38001759, 2023). "This review is aimed at highlighting the roles of TXNIP in the field of diabetology, neurodegenerative diseases, and inflammation." (PMID 33803178, 2021). "This review aims to highlight the roles of TXNIP in the field of diabetology, neurodegenerative diseases, and inflammation." (PMID 33803178, 2021). "We will examine data suggesting TXNIP as a therapeutic target for neurodegenerative diseases where further research is needed." (PMID 33302545, 2020). "The inhibition or the deletion of TXNIP is found to be neuroprotective in cerebrovascular and neurodegenerative diseases." (PMID 32499702, 2020). "Thioredoxin-TXNIP is a major regulator of mitochondrial-mediated oxidative stress in many pathologies including cerebrovascular and neurodegenerative diseases." (PMID 30670947, 2018). "Among the target genes, which are repressed upon BMMF expression are the tumor suppressor genes E2F2 and TXNIP as well as the phospholipase PLA2G6, which is frequently mutated in neurodegenerative diseases." (PMID 29434270, 2018). "Recent reports suggested that activation of TXNIP/NLRP3 axis was positively associated with pain and emotion disorders and the neuroprotective properties by pharmacological inhibition or genetic deletion of TXNIP following cerebrovascular and neurodegenerative diseases." (PMID 33898422, 2021). "Moreover, TXNIP could activate inflammatory factors in neurodegenerative diseases, similar to the results of our study." (PMID 35993020, 2022). "Notably, TXNIP may play an inhibitory role in regulating autophagy in metabolic and degenerative diseases." (PMID 36059548, 2022).
infection (20 papers, 2013 to 2025). The state of being infected such as from the introduction of a foreign agent such as serum, vaccine, antigenic substance or organism. "For example, transitional, naive, memory B cells and atypical memory B cells during acute infection had increased expression of TXNIP, a glucose feedback sensor which inhibits glucose uptake." (PMID 37968278, 2023). "Further, TXNIP expression has been shown to be affected by infection with several oncogenic viruses, including HTLV-I, HBV, HCV, EBV, and KSHV, and the involvement of TXNIP in viral oncogenesis has also been suggested." (PMID 32017809, 2020). "This observed difference in B cell TXNIP expression levels was found to be statistically significant between infection groups." (PMID 32017809, 2020). "Furthermore, HSV-GFP infection assays showed a marked reduction in fluorescence intensity in TXNIP-KO cells, indicating impaired viral replication." (PMID 40628121, 2025). "Additionally, HSV-GFP infection assays confirmed that TXNIP overexpression enhances HSV-1 infectivity." (PMID 40628121, 2025). "Notably, infection-induced dysregulation of immune-related genes (e.g., TXNIP, HO-1 and Prdx5) has been reported, while deletion of the gntR10 gene elevates levels of TNF-α, IL-6 and IL-8 transcripts in infected cells." (PMID 41235247, 2025). "Finally, a large cluster, especially in terms of small RNA regulation upon infection, was “cell proliferation, anti-apoptosis, and oncogenesis,” where EIF2AK2, BIRC3, and TXNIP were significantly upregulated upon infection." (PMID 40510596, 2025). "This study also indicated the crucial role of TXNIP in the RNA virus's infection." (PMID 40628121, 2025). "The mechanism by which the presence of nsp2TF/nsp2N could lead to reduced TXNIP expression in WT infection is unclear." (PMID 35226596, 2022). "In addition, analysis of sorted LN cells demonstrated that the only significant difference in TXNIP expression levels between infection groups occurs in B cells, indicating that vCD200 mainly affects TXNIP expression in this cell type." (PMID 32017809, 2020). "Finally, comparison of infection groups identified the differential expression of host gene thioredoxin interacting protein (TXNIP), suggesting a possible mechanism by which vCD200 negatively affects RRV viral loads in vivo." (PMID 32017809, 2020). "In addition, TXNIP expression has also been found to be affected by infection with several viruses, including human T lymphotropic virus type-I (HTLV-I), hepatitis B virus (HBV), hepatitis C virus (HCV), as well as herpesviruses cytomegalovirus (CMV), Epstein-Barr virus (EBV), and KSHV." (PMID 32017809, 2020). "In summary, this study highlights the critical role of TXNIP in HSV-1 and DENV2 infections and elucidates the molecular mechanism by which TXNIP attenuates the host's antiviral immune response by inhibiting MAVS aggregation and the TBK1-IRF3 signaling pathway." (PMID 40628121, 2025). "Upon infection, a distinct phenotype (subcluster 7.1) emerged among infected cells that shared markers with the highly infected cluster 4, including CITED2, FOS, TXNIP, and CCNG2 genes." (PMID 38896609, 2024). "In addition, two genes, arrestin-related domain-containing protein-3 (ARRDC3) and thioredoxin-interacting protein (TXNIP), stood out among the few genes that were significantly upregulated upon infection with either viruses and in both cell lines." (PMID 33585804, 2021). "The lentivirus plasmid (TXNIP-OV) highly expressed TXNIP protein compared with the empty vector control (E.V) and no transfection group (NT), and the infection efficiency was marked by the GFP fluorescence." (PMID 33274003, 2020). "Nonetheless, TXNIP clearly stands out in the comparison of RNA and TE fold changes as it is both more highly transcribed and more efficiently translated in KO2 than WT (right column), further supporting the conclusion that increased TXNIP expression is a notable feature of KO2 infection." (PMID 35226596, 2022).
cardiovascular diseases (18 papers, 2018 to 2025). "In a recent study including 57 women with GDM, TXNIP levels in trophoblasts correlated positively with aortic intima-media thickness (aIMT), a well-known risk marker of cardiovascular disease in offspring." (PMID 40559375, 2025). "TXNIP has also been linked to the development of cardiovascular disease, as it can promote oxidative stress and inflammation in the vascular endothelium, leading to endothelial dysfunction and atherosclerosis." (PMID 37240157, 2023). "In conclusion, the regulation of cg19693031 TXNIP methylation has been associated with cardiovascular diseases." (PMID 33567593, 2021). "We suggest that the TXNIP DNA hypomethylation associated with smoking is involved in the development of smoking-related pathologies such as cancer and cardiovascular diseases, and is mediated through the TXNIP-NLRP3 interaction." (PMID 32609762, 2020). "Epigenetic modification of TXNIP can increase the risk of cardiovascular disease." (PMID 36910141, 2023). "TXNIP levels can be altered in circulating blood cells, and it could be the signature of a risk factor for cardiovascular diseases." (PMID 33567593, 2021). "In addition to changes in the genomic sequence of TXNIP, epigenetic modifications, mainly influenced by environmental and lifestyle exposures, are also believed to contribute to cardiovascular disease risk." (PMID 33567593, 2021). "Epigenetic modifications of TXNIP are also associated with risks of cardiovascular diseases." (PMID 33567593, 2021). "Current findings reveal that TXNIP inflammasome participates in the pathogenesis of cardiovascular diseases triggered by inflammation." (PMID 35883151, 2022). "TXNIP is a key regulator of metabolism at both cellular and body level and it exerts also a pathological function in several cardiovascular diseases as well as in AD." (PMID 34827650, 2021). "Notably, TXNIP is considered a marker of cardiovascular diseases, including myocardial ischemia, hind limb ischemia, and also cerebral ischemia." (PMID 34827650, 2021). "Additionally, in numerous cardiovascular diseases, TXNIP has recently been identified as a target of miRNAs." (PMID 33567593, 2021). "Interestingly, epigenetic modifications of TXNIP correlate with enhanced risks of cardiovascular diseases." (PMID 34827650, 2021). "Plasma levels of TXNIP may serve as a useful predictor of cardiovascular diseases." (PMID 33567593, 2021). "Thioredoxin interacting protein (TXNIP) is a metabolism- oxidative- and inflammation-related marker induced in cardiovascular diseases and is believed to represent a possible link between metabolism and cellular redox status." (PMID 33567593, 2021). "Similarly, many genes, including CALM2, PDCD4, TXNIP, CYP11B2, P2Y12, and ROCK1, have been identified as downstream targets of GAS5 in cardiovascular diseases." (PMID 38812041, 2024). "H2O2-induced HUVEC senescence was alleviated by Gen via suppressing the TXNIP/NLRP3 axis, which may offer a potential therapeutic approach for improving HUVEC senescence and provide a new direction for the treatment of cardiovascular disease." (PMID 34663173, 2021).
inflammation (13 papers, 2016 to 2026). Aberrant reaction of the microcirculation characterized by movement of fluid and leukocytes from the blood into extravascular tissues. "In the present study, we explored the protective effects of silibinin against SiONPs-induced airway inflammation and explored its underlying mechanism of action, focusing on thioredoxin-interacting protein (TXNIP)/mitogen-activated protein kinases (MAPKs) in vitro and in vivo." (PMID 32164364, 2020). "The decrease in TXNIP was also detected in lung tissues and macrophages obtained from smoking mice, while higher NF-κB activation and lung inflammation occurred simultaneously." (PMID 41107933, 2025). "In summary, findings uncovered in the current study highlighted the protective role of miR-135a-5p in NLRP3-mediated cardiac inflammation and fibrosis through the mechanism wherein miR-135a-5p inhibited TXNIP to reduce the binding of TXNIP and NLRP3." (PMID 35148667, 2022). "In this study, we found that the deletion or downregulation of TXNIP in L-Arg-induced SAP reduced pulmonary inflammation and edema, whereas the overexpression of TXNIP further aggravated the degree of inflammatory cell infiltration and edema." (PMID 36316322, 2022). "Recent studies have reported that exposure to SiONPs elevates the TXNIP expression, activating MAPKs and increasing pulmonary inflammation." (PMID 34829636, 2021). "SZF suppresses the activation of the NLRP3-ASC-caspase-1 axis by inhibiting TXNIP, thus ameliorating renal inflammation." (PMID 29358971, 2017). "Collectively, these findings suggest ROS-mediated TXNIP serves as a key regulatory factor, and AD may serve as a potential therapeutic agent for pulmonary inflammation." (PMID 42041533, 2026). "Thus, the anti‐inflammatory and anti‐oxidant effects of linarin may play a major role in the protective effects of DO in airway inflammation of the LPS‐induced ALI model by inhibiting the TXNIP/NLRP3 inflammasome and activating the Nrf‐2 pathways." (PMID 40265676, 2025). "In the present study, we observed high expression of mitochondrial ROS and TXNIP in cardiac tissue, which triggered NLRP3 overexpression and cardiac inflammation." (PMID 34257682, 2021).
kidney diseases (7 papers, 2018 to 2025). "By preventing this transformation, TXNIP inhibition could offer a novel preventative strategy against the calcification of the vascular matrix, which is a hallmark of several metabolic and kidney diseases." (PMID 40610750, 2025). "There is a strong relationship between NLRP3 inflammasome and TXNIP in the development of kidney diseases." (PMID 29849929, 2018). "TXNIP has been reported to play an important role in regulating the inflammatory response and deletion of TXNIP has been shown to attenuate the inflammatory response and fibrosis in kidney disease." (PMID 36316322, 2022). "Beyond that, NAC also could inhibit TXNIP production in nondiabetic kidney diseases." (PMID 36186658, 2022).
neurological diseases (5 papers, 2021 to 2024). "In reference to a great many studies, TXNIP participates in regulating oxidative stress, inflammation, vascular dysfunction and cellular stress in neurological diseases." (PMID 34348577, 2021). "Therefore, exploring the direct interaction between TXNIP and NLRP3 is essential for studying neurological diseases related to the ROS/TXNIP/NLRP3 signaling pathway." (PMID 35721021, 2022). "Additionally, it provides more data support for TXNIP/NLRP3 as a potential target for treating neurological diseases." (PMID 34348577, 2021). "It is often necessary to consider the interaction of TXNIP and NLR family, domain of pyrin containing 3 (NLRP3) in neurological diseases." (PMID 34348577, 2021). "Our research may provide potential targets for inhibitor development based on the ROS/TXNIP/NLRP3 signaling pathway, which may be useful for future therapeutic studies on neuroinflammation and related neurological diseases." (PMID 35721021, 2022).
brain diseases (4 papers, 2020 to 2023). "The activation of inflammasome and apoptosis caused by TXNIP are widespread in brain diseases." (PMID 35721021, 2022). "In addition, as dysfunctions in glucose and cellular metabolism have been associated with such brain diseases, a role for TXNIP in neurodegeneration has actively been investigated." (PMID 33302545, 2020). "For this review focusing on brain diseases with inflammatory components, we will consider TXNIP expression in macrophages and its consequences on inflammation." (PMID 33302545, 2020). "Without this knowledge, identifying sites of TXNIP activity in relation to neuropathology, identifying the neuroanatomical distribution and cell types mediating TXNIP activity in particular, will hinder progress on developing TXNIP as a therapeutic target for brain diseases." (PMID 33302545, 2020).